RAI1 (retinoic acid induced 1)
Diseases named in the same sentence as RAI1 in open-access papers (continued):
Sharing a sentence is not in itself a finding about the gene and the disease.
Obesity (continued). "A mouse model for SMS has been engineered and Rai1 haplo-insufficient mice recapitulate some of the SMS features such as obesity and craniofacial phenotypes." (PMID 28548639, 2017). "Consistent with a role of HDAC4 in the development of obesity, deletion in or mutation of HDAC4 was reported as resulting in reduced expression of the retinoic acid induced 1 (RAI1) gene, whose haploinsufficiency leads to obesity in SMS." (PMID 25411582, 2014). "Truncal-abdominal obesity is observed in a majority of SMS patients during early adolescence and other SMS mouse models have shown obesity phenotypes, further implicating RAI1 as a contributor to obesity and body weight." (PMID 25127133, 2014). "We conclude that the dosage or steady state expression level of RAI1/Rai1 is unlikely the sole or major contributor to the obesity opposing and protective metabolic phenotypes observed in the PTLS mice." (PMID 22654670, 2012). "RAI1 haploinsufficiency has emerged as a monogenic model for obesity." (PMID 40437981, 2025). "The haploinsufficiency of RAI1 in Vglut2+ neurons is associated with motor delays, obesity, and, when RAI1 is absent, learning deficits; meanwhile, in Gad2+ neurons, RAI1 loss leads to learning deficits." (PMID 40724914, 2025). "Interestingly, deletion of Rai1 during adolescence or adulthood in mice leads to normal neurobehavior but induces adult-onset obesity along with reduced Bdnf expression." (PMID 39766920, 2024). "Because GABAergic Rai1 loss did not induce obesity and most BDNF-producing neurons are glutamatergic." (PMID 37956053, 2023). "Twenty percent of SMS patients do not have 17p11.2 deletions but instead carry RAI1 point mutations that are still frequently associated with obesity." (PMID 37956053, 2023). "In contrast, obesity could be induced by ablating Rai1 from Sim1-lineage neurons and, to a lesser extent, SF1-lineage neurons." (PMID 37956053, 2023). "Building on these studies, we hypothesize that obesity and neurobehavioral features in SMS mice can be partially mitigated using gene therapy that enhances expression of the remaining Rai1 allele in the PVH during early adolescence." (PMID 36410433, 2022). "Rai1 heterozygous mice (hereafter, SMS mice) exhibit three hallmark disease features: increased repetitive rearing, impaired social dominance, and hyperphagic obesity." (PMID 36410433, 2022). "Our work shows that neurobehavioral features and obesity in SMS mice are caused by Rai1 loss in subcortical but not cortical glutamatergic neurons." (PMID 36410433, 2022). "Our recent work found that PVH-specific Bdnf overexpression during early adolescence fully reverses obesity in SMS mice, suggesting that postnatal manipulation of the Bdnf signaling could be more effective than increasing Rai1 for treating obesity." (PMID 36410433, 2022). "Interestingly, Bdnf is also downregulated in the hypothalamus of Rai1+/− mice, which are hyperphagic, have impaired satiety, develop obesity, and consume more food during light phase." (PMID 30819258, 2019). "The RAI1 gene has also been implicated in glucose and lipid metabolism, potentially predisposing individuals to insulin resistance even in the absence of severe obesity." (PMID 40443456, 2025). "Therefore, Rai1 function in these neurons could contribute to obesity in SMS, a topic that awaits future investigation." (PMID 37956053, 2023). "Interestingly, RAI1 may have a sexually dimorphic function as female SMS mice exhibit more pronounced obesity than males." (PMID 37956053, 2023). "Finally, we characterized the effects of diet in Rai1+/− mice on the development of obesity and asked if dietary regimens could modify obesity outcomes." (PMID 25127133, 2014). "Since the first report of RAI1 haploinsufficiency syndrome in 1986, little is known about the metabolic implications of SMS, which is marked by the occurrence of early-onset obesity." (PMID 37761412, 2023).
Obesity (continued). "Within subcortical structures, deleting Rai1 from one region, the paraventricular nucleus of hypothalamus (PVH) was sufficient to induce SMS-like obesity in mice." (PMID 36410433, 2022). "Rai1 heterozygous mice display some mild SMS-like symptoms, including obesity, circadian abnormalities, and characteristic craniofacial features." (PMID 34576033, 2021). "We performed breeding studies by generating Rai1+/− mice in a mixed genetic background of C57Bl/6J and FVB/NJ and characterized the offspring for the development of obesity through adolescence and adulthood." (PMID 25127133, 2014). "While not significantly correlated, the presence of hearing loss, seizures, hoarse voice, childhood onset of obesity and specific behavioral aspects and the absence of immunologic abnormalities and cardiovascular or renal structural anomalies, appeared to be specific for the de novo RAI1 subgroup." (PMID 21857958, 2011). "Although many authors believe that retinoic acid-induced 1 (RAI1), localized in chromosome band 17p11.2, alone is responsible for the obese phenotype, we speculate that the reduced CSN could be an additional reason for the appearance of obesity after 10 years." (PMID 40149914, 2025). "Our previous work found that deleting Rai1 from cortical excitatory neurons using an Emx1Cre allele, from the GABAergic neurons using a Gad2Cre allele, or from astrocytes using a GfapCre allele did not induce SMS-like obesity." (PMID 37956053, 2023). "RAI1’s regulation of BDNF in the hypothalamus may contribute to the hyperphagia and obesity seen in Smith–Magenis syndrome and haploinsufficiency of RAI1 results in abnormal expression of a number of genes associated with obesity, including proopiomelanocortin (POMC)." (PMID 24519454, 2015). "Notably, mice lacking one copy of Rai1 in the BDNF-producing cells do not exhibit obesity, whereas SMS patients and SMS mice show pronounced obesity." (PMID 37956053, 2023).
Intellectual disability (14 papers, 2011 to 2025). "A genetic diagnosis was obtained at a median of 40.5 months (11 to 112 months, n = 20): 75% of patients (15/20) were carriers of a chromosome 17 microdeletion (diagnosed by FISH or CGH) and 25% (5/20) of a RAI1 gene mutation (diagnosed from intellectual disability gene panels)." (PMID 41300589, 2025). "Smith–Magenis syndrome (SMS) is a neurodevelopmental disorder associated with intellectual disability, sleep disturbance, early-onset obesity, and extensive behavioral deficits, caused by a heterozygous microdeletion containing retinoic acid-induced gene 1 (RAI1) or by a mutation within RAI1." (PMID 33261141, 2020). "Previous studies have shown that dysregulation of the RAI1 gene in the brain leads to intellectual disabilities such as Smith–Magenis syndrome and Potocki–Lupski syndrome." (PMID 35456427, 2022). "These holistic studies of RAI1 and its interactions allow insights into SMS and other disorders associated with intellectual disability and behavioral abnormalities." (PMID 27799067, 2016). "Participant 176 is a 37-month-old male with ROHs noted on chromosomes 3, 17, and 22 within regions where several genes (i.e., POU1F1, RAI1, and EP300) associated with intellectual disability are found." (PMID 25400949, 2014). "Consistent with previously published reports, our de novo RAI1 variant cases were less cognitively impaired (mild intellectual disability), lacked short stature (except for outlier M2543), and had normal cardiac and renal structure." (PMID 21857958, 2011).
schizophrenia (12 papers, 2010 to 2025). A major psychotic disorder characterized by abnormalities in the perception or expression of reality. "RAI1 is also associated with neurodevelopmental disorders that are pervasive into adulthood including schizophrenia and autism as well as adult diseases such as Parkinson’s disease and cerebellar ataxia." (PMID 24519454, 2015). "A polymorphic CAG repeat is present in the N-terminus of the RAI1 protein, the length of which is associated with the age of onset of spinocerebellar ataxia type 2 and the response to neuroleptic medication in schizophrenia." (PMID 20738874, 2010). "Further, RAI1 may be linked to adult neural disorders with developmental origins such as schizophrenia and autism." (PMID 24519454, 2015). "However, the underlying mechanisms through which the RAI1 gene is overexpressed in patients with schizophrenia are still unknown." (PMID 35456427, 2022). "Specifically, one study showed that patients with schizophrenia and bipolar disorder had a significant increase in RAI1 expression in their brains." (PMID 35456427, 2022). "The RAI1 gene has also been indirectly associated with spinocerebellar ataxia (SCA2), schizophrenia, and autism." (PMID 29794985, 2018). "Bdnf, a neurotrophic growth factor, whose reduced expression has been identified in depression, schizophrenia and obsessive-compulsive disorder in human and animal models, was also found to be downregulated in Rai1+/− mice." (PMID 29794985, 2018). "RAI1 is thought to be key to normal brain development and function due to its association with a number of neurobehavioral disorders which, besides SMS, include Potocki–Lupski syndrome, schizophrenia, autism, Parkinson disease, and cerebellar ataxia." (PMID 28548639, 2017). "In addition, the RAI1 gene has also been associated with spinocerebellar ataxia (SCA2), schizophrenia, and autism." (PMID 28448442, 2017). "At the N-terminus of the RAI1 protein there is a polymorphic CAG repeat, which length is associated with the age of onset of spinocerebellar ataxia type 2 and the response to neuroleptic medication in schizophrenia." (PMID 21629438, 2010). "In addition, the human RAI1 gene has been implicated in several neurobehavioral traits as spinocerebellar ataxia (SCA2), schizophrenia and non syndromic autism." (PMID 21629438, 2010). "In addition to this, RAI1 gene was associated with spinocerebellar ataxia (SCA2), neuroleptic response in patients with schizophrenia, neurobehavioral traits manifested in SMS patients with RAI1 loss-of-function alleles and non syndromic autism." (PMID 20738874, 2010). "This review highlights the role of RAI1 in a range of neuropsychiatric diseases, including SMS, PTLS, SCA, ASD, schizophrenia, bipolar disorder and major depression." (PMID 40437981, 2025). "Additionally, we summarised research progress on RAI1 in SCA, ASD, schizophrenia, bipolar disorder and major depression." (PMID 40437981, 2025). "In particular, the expression levels of the murine orthologs of the two genes RAI1 (GeneID: 10743) and SREBF1 (6720), which were associated with schizophrenia, a phenotype absent from SMS and PTLS patients, show a strong relationship with gene dosage." (PMID 21124890, 2010).
autism (10 papers, 2009 to 2024). Persistent deficits in social interaction and communication and interaction as well as a markedly restricted repertoire of activity and interest as well as repetitive patterns of behavior. "RAI1 is not only the causal gene for a small fraction of patients with syndromic autism, but also a gene crucial for normal development of neural systems." (PMID 38674394, 2024). "We have identified a rare de novo RAI1 missense mutation, p.R1147Q, in a patient diagnosed with autism by DSM-IV." (PMID 29794985, 2018). "Taken together, our findings suggest that the RAI1 gene mutations may contribute to some cases of autism." (PMID 29794985, 2018). "Despite the high incidence of autism in the group of patients harboring the common deletion (~90%) the incidence of autism in the group of patients carrying a Rai1 point mutation is still unknown." (PMID 28448442, 2017). "In addition, RAI1 has been shown to be associated with non syndromic autism." (PMID 21629438, 2010). "Moreover, RAI1 was recently associated with non syndromic autism." (PMID 20738874, 2010). "Observations from clinical cases and animal models also suggest that changes of RAI1 expression levels contribute to autism." (PMID 38674394, 2024). "Here we report a patient with autism as the main clinical presentation, with some SMS-like features and a rare de novo RAI1 gene mutation, c.3440G > A (p.R1147Q)." (PMID 29794985, 2018). "In addition to autism, the proband had other clinical features, such as cognitive impairment, motor delay, sleep disturbance, aggressive behavior, hyperactivity, and irregular eating patterns, as commonly seen in patients with the RAI1 gene deletions or mutations." (PMID 29794985, 2018). "Thus, we performed next generation diagnostic panel sequencing that included the RAI1 gene and an additional 61 autosomal and X-linked genes known for their association with ASD and/or syndromes that include autism as a significant clinical feature." (PMID 29794985, 2018). "Recently, in a study with a group of patients with non-complex-autism, RAI1 was found to be one of the novel autism candidate genes within the autism-associated CNVs regions." (PMID 21629438, 2010).
Potocki-Lupski syndrome (9 papers, 2010 to 2023). "RAI1 has numerous developmental functions in the RA pathway, and mutations in this gene are responsible for Smith-Magenis and Potocki-Lupski syndromes in humans." (PMID 29950181, 2018). "Although RAI1 haploinsufficiency is responsible for SMS, RAI1 duplication causes a different neurodevelopmental disorder with a similar clinical presentation, namely, Potocki-Lupski syndrome (PTLS, OMIM# 610883)." (PMID 36411275, 2022). "RAI1 is a dosage-sensitive gene whose decreased or increased expression by recurrent and non-recurrent 17p11.2 deletions or duplications causes Smith-Magenis (SMS) or Potocki-Lupski syndromes (PTLS), respectively." (PMID 35821519, 2022). "Studies on mouse models and humans indicate that RAI1 is likely the dosage sensitive gene responsible for clinical features in the Potocki-Lupski Syndrome (PTLS), (OMIM# 610883) a neurobehavioral disorder with autistic features that is caused by reciprocal duplication of the 17p11.2 region." (PMID 20738874, 2010).
spinocerebellar ataxia (7 papers, 2010 to 2025). "For instance, expansion of cytosine–adenine–guanine (CAG) repeats in RAI1 has been implicated in modifying spinocerebellar ataxia (SCA) (Ref." (PMID 40437981, 2025).
Anxiety (5 papers, 2009 to 2025). Intense feelings of nervousness, tension, or panic often arise in response to interpersonal stresses. "In addition, anxiety issues, rapid mood shifts and emotional lability were present in 5/5 of our de novo RAI1 variant group, raising future research questions concerning the role of RAI1 in neurodevelopment." (PMID 21857958, 2011). "While SMS mice spent more time in the center, this was not due to reduced anxiety because WT and SMS mice treated with control rAAV8 show similar anxiety levels in the elevated plus maze, consistent with our previous findings that indicate Rai1 loss does not induce anxiety in mice." (PMID 36410433, 2022).
Cognitive impairment (5 papers, 2009 to 2025). Abnormal cognition is characterized by deficits in thinking, reasoning, or remembering. "In SMS and PTLS, RAI1 mutations lead to clear neurological and behavioural challenges, including developmental delays, sleep disturbances and cognitive impairments." (PMID 40437981, 2025). "Lipid and metabolic disorders, behavioral problems, sleep disturbances, and cognitive impairments represent contrasting and mirrored clinical features of SMS and PTLS, underscoring the exquisite sensitivity of cells to RAI1 in regulating key biological processes." (PMID 40724914, 2025).
depression (5 papers, 2016 to 2025). "Of thirteen depression‐associated DRPs, seven proteins including DDC, FGFR2, KIBRA, MED22, OLIG1, RAI1, SLIT2 were upregulated, whereas six proteins including COX3, CRHBP, CSMD1, FSTL1, GRIK4, and LMTK3 were downregulated." (PMID 39373701, 2024).
sleep disorder (5 papers, 2015 to 2024). A change from the patient's baseline sleeping pattern, in the hours slept and/or an alteration/dysfunction in the stages of sleep. "Although the most penetrant symptoms of SMS such as sleep disorders are associated with heterozygous loss of RAI1, linkage studies suggest that loss of other genes within the deletion region contribute to aspects of the syndrome." (PMID 38940292, 2024).
epilepsy (4 papers, 2010 to 2025). A brain disorder characterized by episodes of abnormally increased neuronal discharge resulting in transient episodes of sensory or motor neurological dysfunction, or psychic dysfunction. "However, in the basic research review section, we primarily focused on summarising the currently more extensive and in-depth mechanistic studies, specifically those related to the mechanisms of RAI1 in regulating weight, circadian rhythm and epilepsy." (PMID 40437981, 2025). "Integrating findings from animal studies, particularly those examining the regulatory mechanisms of RAI1 in critical phenotypes, such as body weight, sleep and epilepsy, underscores the precise regulation of RAI1 expression in maintaining various nervous system functions." (PMID 40437981, 2025). "The top candidate genes found upregulated due to RAI1 haploinsufficiency are ZIC1, PSEN2, RXRB, CLN8 and SCN12A being involved in neurogenesis, mental retardation, sensory transmission, nociceptive behavior, epilepsy and neurological function." (PMID 21629438, 2010).
neuroblastoma (3 papers, 2010 to 2024). Neuroblastoma (NB) is the most common solid, extracranial childhood tumor. "Since we found that Rai1 activity was dependent of cellular type, we performed all our studies in mouse Neuro-2a neuroblastoma cells." (PMID 20738874, 2010). "Based on this we wanted to examine whether Rai1 has a different transactivation activity in cells derived from murine neuroblastoma, the Neuro-2a cell line." (PMID 20738874, 2010). "To further examine whether endogenous RAI1 can be localized to the cytoplasm, we studied endogenous RAI1 in the SH-SY5Y human neuroblastoma cell, in which RAI1 expression has not previously been investigated." (PMID 24519454, 2015).
Parkinson disease (3 papers, 2017 to 2024). A progressive degenerative disorder of the central nervous system characterized by loss of dopamine producing neurons in the substantia nigra and the presence of Lewy bodies in the substantia nigra and locus coeruleus. "The co-occurrence of SMS and EOPD in this patient is noteworthy, as recent studies have suggested a potential association between the RAI1 gene and Parkinson’s disease pathogenesis." (PMID 39126013, 2024). "Pathogenic variants of RAI1 may result in an inversion of circadian melatonin secretion with a lack of nocturnal melatonin, which may play a role in the development of parkinsonism." (PMID 36699000, 2022).
Angelman syndrome (2 papers, 2014 to 2022). A neurogenetic disorder characterized by severe intellectual deficit and distinct facial dysmorphic features.
developmental disability (2 papers, 2016). Disorders in which there is a delay in development based on that expected for a given age level or stage of development. "Thus, we could not conclusively rule out that this missense variant in RAI1 is contributing to the phenotype present in patient 1, but her more severe developmental disability compared with her father and sister warranted further work-up." (PMID 26739615, 2016).
dyslipidemia (2 papers, 2014 to 2023). "From our analysis, no patients with RAI1 variants had dyslipidemia, and a strong negative correlation was found between BMI percentiles and HDL." (PMID 37761412, 2023). "However, a recent study has shown that mice carrying a chromosomal deletion of Rai1 (and several other genes) commonly found amongst individuals with SMS display a range of phenotypic features manifesting metabolic syndrome." (PMID 25127133, 2014).